PDGFRA (platelet derived growth factor receptor alpha)
Diseases named in the same sentence as PDGFRA in open-access papers (continued):
Sharing a sentence is not in itself a finding about the gene and the disease.
Hepatitis (1 paper, 2018). Inflammation of the liver. "Immunohistochemistry showed expression of PDGFRα at the hepatocyte membrane and in nonparenchymal cells in the liver with hepatitis, whereas the normal liver exhibited no PDGFRα staining." (PMID 30509307, 2018). "Expression of PDGFRα was examined in normal human liver and human liver with hepatitis but not advanced fibrosis." (PMID 30509307, 2018). "Whole-cell lysates from livers with pathologically proven hepatitis but not advanced fibrosis (n = 7) were examined for col1α(I) and PDGFRα expression and compared to that in normal liver tissue (n = 7)." (PMID 30509307, 2018).
hyperandrogenism (1 paper, 2017). Excessive secretion of androgens from the adrenal glands or gonads. "We also discovered that PDGFRA, a cell surface tyrosine kinase receptor involved in mesenchymal cell proliferation and male-specific mesonephric cell migration, is found up-regulated in obese PCOS women, which may contribute to the hyperandrogenism and appearance male characters." (PMID 29050221, 2017).
hyperuricemia (1 paper, 2025). An abnormally high level of uric acid. "For example, in hyperuricemia, we identified ADR-DP proteins that included PDGFRA, FLT3, and ABL1 as having high values in the z axis." (PMID 39954672, 2025).
keratoconus (1 paper, 2017). A degenerative, structural disorder of the eye, characterized by a cone-shaped protrusion of the cornea. "Indeed, while in control corneas CD34+/PDGFRα+ TC were typically found in the whole corneal stroma, in keratoconus a patchy loss of CD34/PDGFRα immunoreactivity was observed mainly in the subepithelial part of the stroma." (PMID 28714595, 2017).
kidney cancer (1 paper, 2025). Primary or metastatic malignant neoplasm involving the kidney. "Data on the expression and prognostic role of PDGFRα and PDGFRβ in kidney cancer are scarce and require further research." (PMID 40434293, 2025).
lacrimal gland disease (1 paper, 2025). "Avapritinib showed a particularly prominent specificity for lacrimal gland disease, which may be related to the role of KIT/PDGFRA inhibition in the lacrimal secretion pathway." (PMID 40951360, 2025).
latent infection (1 paper, 2023). "Our study unravels that MCMV commonly persists in PDGFRα+ fibroblastic cells for the long term, in a state that fulfils all the formal criteria of latent infection." (PMID 37248241, 2023). "Next, we investigated if PDGFRα+ FC that carried viral genomes during MCMV latency in vivo fulfilled the formal criteria of latent infection." (PMID 37248241, 2023).
lupus (1 paper, 2018). "This is in agreement with our results as we detected Nestin+Sca1+PDGFRα+CD45− MSCs and T cells in the pelvis wall of autoantibody negative lupus-prone mice." (PMID 29777158, 2018).
lupus nephritis (1 paper, 2016). Glomerulonephritis in the context of systemic lupus erythematosus. "Intrarenal mRNA levels of PDGFRA are significantly enriched in patients with lupus nephritis." (PMID 27642302, 2016).
malignant mesothelioma (1 paper, 2020). A malignant neoplasm of the pleura or peritoneum, arising from mesothelial cells. "Similarly, male patients with malignant mesothelioma had significantly more often PDGFRα expression than women (6/9 men versus 0/6 women; p = 0.017)." (PMID 33114048, 2020).
mammary adenocarcinoma (1 paper, 2025). "A recent study on mammary adenocarcinoma showed that perivascular LYVE1+ TAMs secrete the platelet-derived growth factor-C (PDGF-C) homodimer, PDGF-CC, which signals to PDGF receptor-α (PDGFRA)-expressing stromal cells involved in blood vessel formation." (PMID 41203997, 2025).
metastatic cancers (1 paper, 2020). A carcinoma which has spread from the original site of growth to another anatomic site. "In addition, another study showed that massively parallel sequencing coupled with dose-adjusted gemcitabine/carboplatin treatment of metastatic cancers with mutations in PDGFRA, SMAD4, and CDKN2A may lead to improved outcome." (PMID 32839457, 2020).
Moyamoya disease (1 paper, 2024). Moyamoya disease (MMD) is a rare intracranial arteriopathy involving progressive stenosis of the cerebral vasculature located at the base of the brain causing transient ischemic attacks or strokes. "PDGFRα’s role in angiogenesis was also shown in patients with Moyamoya disease, in which PDGFRα signals play an important role in developing spontaneous angiogenesis between the temporal muscle and the neocortex." (PMID 38673853, 2024).
muscle disorders (1 paper, 2018). "The major contributor to ectopic fibro-fatty formation in several muscle disorders is a population of non-myogenic mesenchymal cells, called fibro/adipogenic progenitors (FAPs), that can be identified by the expression of platelet-derived growth factor receptor alpha (PDGFRα)." (PMID 29463296, 2018).
muscular dystrophy (1 paper, 2021). Muscular dystrophy (MD) refers to a group of more than 30 genetic diseases characterized by progressive weakness and degeneration of the skeletal muscles that control movement. "The authors demonstrated that seven days after acute intramuscular injury, a large proportion of perilipin+ adipocytes derived from PDGFRα+ FAPs, indicating that PDGFRα expressing progenitors are the major source of damage-induced fat cells in normal muscle regeneration and in muscular dystrophy." (PMID 34210364, 2021).
myxoid liposarcoma (1 paper, 2016). A liposarcoma characterized by the presence of round non-lipogenic primitive mesenchymal cells and small signet ring lipoblasts within a myxoid stoma with a branching vascular pattern. "Together, these data demonstrate that the contribution of FUS-CHOP expression to myxoid liposarcoma cell growth is significant and that targeting the fusion gene and/or its downstream targets such as VEGFR1 and PDGFRα induces significant inhibition of myxoid liposarcoma tumor growth." (PMID 27822137, 2016).
nephritis (1 paper, 2017). Inflammation of renal tissue. "We confirmed that PDGFRα was expressed in mesangial regions in mice with anti-GBM nephritis, and confirmed minor contribution of bone marrow-derived cells." (PMID 28191821, 2017). "PDGFRα was predominantly expressed by mesangial cells in normal glomeruli, and its expression was increased after induction of anti-GBM nephritis." (PMID 28191821, 2017). "Thirdly, we also established PDGFRα promoter-driven CTGF conditional KO (Pdgfra-CTGF cKO) mice, which predominantly lack CTGF expression in mesangial cells of the glomeruli, to investigate the cell type-specific contribution of CTGF in anti-GBM nephritis model." (PMID 28191821, 2017).
neurocytoma (1 paper, 2022). "Our additional studies of PHF14 function in several cell lines corroborated by a single neurocytoma primary culture point to a putative regulatory role of PHF14 in modulating cell proliferation, PDGFRα expression and sensitivity to the anti-proliferative effect of the PDGFR inhibitor Sunitinib." (PMID 36359362, 2022).
Noonan syndrome (1 paper, 2021). Noonan Syndrome (NS) is characterized by short stature, typical facial dysmorphism and congenital heart defects. "Likewise, in BAMS, we observed a slight but non-significant decrease in PTPN11 expression (FC −0.69, p-value = 6.01 × 10−06), encoding SHP-2 that binds to PDGFRα and is also associated with facial dysmorphism in Noonan syndrome, further underlining the importance of this signaling pathway in BAMS." (PMID 34209568, 2021).
oligodendroglial tumor (1 paper, 2016). Oligodendrogliomas are cerebral tumors that are differentiated from other gliomas on the basis of their unique genetic characteristics and better response to chemotherapy. "Aside from codeletion of 1p/19q, oligodendroglial tumors are strongly associated with mutations of IDH1/2, TERT promoter (TERTp) and they are also associated with methylation of MGMT and upregulation of PDGFRA." (PMID 27556304, 2016). "Among this 1p/19q intact oligodendroglial tumor cohort, 58 cases demonstrated classic oligodendroglial histology which showed older patient age, better prognosis, association with grade III histology, PDGFRA expression, TERTp mutation, as well as frequent IDH mutation." (PMID 27556304, 2016).
oncocytoma (1 paper, 2019). "ErbB4, Insulin R, and IGF-1R were phosphorylated in the papillary RCC (RE0020), Mer (Axl family) was phosphorylated in the oncocytoma (RE0150), and HGFR, PDGFRα, and PDGFRβ were phosphorylated in the renal pelvic carcinoma (RE0210)." (PMID 31690270, 2019).
Osteochondroma (1 paper, 2018). A common, benign cartiliginous neoplasm arising from the metaphysis of bone. "Although it remains formally possible that osteochondromas progressed to HO in Pdgfrα-R206H mice, such an occurrence is rare in human FOP." (PMID 30226468, 2018). "Second, while palovarotene reduced severity of whole-body HO and inhibited osteochondroma formation in Pdgfrα-R206H mice, palovarotene treatment of Acvr1[R206H]FlEx/+;Prrx1-Cre mice resulted in more marked reductions in HO." (PMID 30226468, 2018). "(I–M) 0.735 mg/kg PVO-treated and (N–R) 1.47 mg/kg PVO-treated Pdgfrα-R206H mice exhibited reduced HO (arrows), and (J, O, P) osteochondromas were often absent (asterisks)." (PMID 30226468, 2018).
osteonecrosis of (1 paper, 2023). "The Venn diagrams showed six intersecting genes related to osteonecrosis of the femoral head, OS and APO targets: NFE2L2 (Nrf2), ERN1, PDGFRB, PDGFRA, KEAP1 and CDK1." (PMID 37749949, 2023).
overactive bladder (1 paper, 2022). Symptom of overactive detrusor muscle of the urinary bladder that contracts with abnormally high frequency and urgency. "Reports indicate altered urinary expression of PDGFRα, Trp channels and other interstitial cell markers in human patients and animal models of bladder dysfunction including IC/BPS, overactive bladder (OAB), spinal cord injury (SCI)-induced OAB, and bladder outlet obstruction." (PMID 35528149, 2022).
Parkinson disease (1 paper, 2017). A progressive degenerative disorder of the central nervous system characterized by loss of dopamine producing neurons in the substantia nigra and the presence of Lewy bodies in the substantia nigra and locus coeruleus. "In addition, recent studies in animal models of Alzheimer’s and Parkinson’s disease have shown significant benefit from treatment with the related PDGFRα antagonists Nilotinib and Bosutinib." (PMID 28725968, 2017).
PEComas (1 paper, 2016). "In contrast to the case of GISTs, PDGFRα positivity and mutations in PDGFRα genes have not been reported in PEComas, to the best of our knowledge." (PMID 27842558, 2016).
phyllodes tumor (1 paper, 2013). A benign, borderline, or malignant fibroepithelial neoplasm arising from the breast and rarely the prostate gland. "Expression of both PDGFRα and β have already been described in phyllodes tumors and have been associated with high histologic grade and worse prognosis." (PMID 23895135, 2013).
PN tumors (1 paper, 2025). "MES tumors are characterized by high NF1 expression, while PN tumors frequently exhibit PDGFRA mutations and contain tumor cells similar to oligodendrocyte progenitors and neural progenitors." (PMID 40331985, 2025).
preeclampsia (1 paper, 2022). Preeclampsia is a hypertensive disorder of pregnancy that is characterized by new-onset hypertension with proteinuria presenting after 20 weeks of gestation, and depending on mild or severe forms may initially present with severe headache, visual disturbances, and hyperreflexia. "A previous study reported that hsa-miR-342-3p inhibited the proliferation, migration, invasion and G1/S phase transition of HTR8/SVneo cells by suppressing PDGFRA in women with preeclampsia." (PMID 36615122, 2022).
prion disease (1 paper, 2024). A transmissible disease that is caused by a protein that is able to induce abnormal folding of normal cellular proteins, leading to characteristic spongiform brain changes, which are associated with neuronal loss without an inflammatory response. "To investigate the effects of NG2 glia depletion on prion disease in vivo, we crossed Pdgfrα-CreER mice with iDTR mice and generated Pdgfrα-CreER/iDTR (PdgfrαiDTR) mice." (PMID 38802591, 2024).
psoriasis (1 paper, 2015). An autoimmune condition characterized by red, well-delineated plaques with silvery scales that are usually on the extensor surfaces and scalp. "The reaction for PDGFRα was increased in the papillary dermis of the lesional dermis, probably in the context of the chronic inflammation that characterizes psoriasis." (PMID 25991475, 2015).
pulmonary adenoid cystic carcinoma (1 paper, 2015). "The data presented in this work suggest that EGFR, KRAS, BRAF, ALK, PIK3CA, PDGFRA, and DDR2 may not be driver genes in primary pulmonary adenoid cystic carcinoma." (PMID 26373952, 2015).
rectum adenocarcinoma (1 paper, 2020). An adenocarcinoma arising from the rectum. "This is the case for rectum adenocarcinoma: its five oncogenes are BCL2, KIT, KLF4, MET, and PDGFRA." (PMID 31900418, 2020).
refractive error (1 paper, 2013). A defect in the focusing of light on the retina as in astigmatism, myopia, or hyperopia. "In terms of identifying genetic variants that influence susceptibility to disorders such as refractive error, variants that affect the expression level or function of PDGFRA would not seem likely candidates given this pleiotropic scaling role." (PMID 23401653, 2013).
retinal detachment (1 paper, 2012). An eye emergency condition which may lead to blindness if left untreated. "The next step would be a series of experiments in retinal detachment models looking at intraretinal GFAP and PDGFRα expression." (PMID 22966235, 2012).
sarcopenia (1 paper, 2021). Progressive decline in muscle mass due to aging which results in decreased functional capacity of muscles. "We also generated PDGFRα+ cell-depleted mice and demonstrated that mesenchymal progenitor depletion leads to phenotypes markedly similar to sarcopenia, including a loss of muscle mass and strength, myofiber atrophy, and degeneration of neuromuscular junctions." (PMID 34638584, 2021).
silicosis (1 paper, 2023). Silicosis is a respiratory disease caused by breathing in (inhaling) silica dust. "Quantitation of total lung PDGFRα+ fibroblasts by flow cytometry resulted in a 1.74-fold decrease after treatment with ABT-263 compared with mice with silicosis treated with vehicle (P = 0.43)." (PMID 36752201, 2023).
Spina bifida occulta (1 paper, 2016). The closed form of spina bifida with incomplete closure of a vertebral body with intact overlying skin. "The severe and fully penetrant spina bifida occulta observed here in Pdgfc−/−; PdgfraGFP/+ mice suggest that this overlapping function is mediated by PDGFRα." (PMID 26988758, 2016).
spinal cord tumor (1 paper, 2025). "Mangiola and colleagues conducted a study focused on the inhibition of PDGFRα and observed a significant reduction in spinal cord tumor cell proliferation by approximately 38 ± 9.5%, alongside a decrease in PDGFRα expression levels." (PMID 40942013, 2025).
squamous non-small cell lung cancer (1 paper, 2016). "NCI-H1703 is a squamous non-small cell lung cancer (NSCLC) cell line that harbors both FGFR1 and PDGFRA amplifications." (PMID 27223434, 2016).
steatosis (1 paper, 2020). Increased lipid within the cytoplasm of cells. "The severity of steatosis was scored and ranked, demonstrating significant differences between Creneg and Pdgfrα-Crepos mice on HFD (p<0.05, Wilcoxon Rank-Sum)." (PMID 32730300, 2020). "Interestingly, Pdgfrα-Crepos Ahr knockout mice on HFD exhibited no steatosis, with less than 5% of hepatocytes containing lipid vacuoles in all samples examined." (PMID 32730300, 2020).
tendinopathy (1 paper, 2024). "Due to the fact that LET and other tendinopathies are caused by mechanical overload, PDGFRα’s activity seems to be very important in the treatment of these conditions." (PMID 38673853, 2024). "For these reasons, PDGFRα appears to be strongly involved in the development of tendinopathy, its treatment and the effects of PRP." (PMID 38673853, 2024). "However, in order to fully understand the involvement of PDGFRα in the development of tendinopathy, its treatment and its effects on platelets, further research is necessary." (PMID 38673853, 2024). "There are no studies in the literature assessing the effect of PDGFRα on angiogenesis in the course of tendinopathy, although it was shown that PDGFR-blocked tendons show deficits in neovascularization." (PMID 38673853, 2024).
thymic tumor (1 paper, 2015). "We aimed to analyze genotypes of VEGF-A, VEGFR2, Flt4, PDGFRα, HIF-1α and ERCC1 and their correlation with thymic tumor risk and patient outcome." (PMID 26254278, 2015).
Wilms’ tumor of the kidney (1 paper, 2013). "In Wilms’ tumor of the kidney, PDGF-A and PDGFRα was expressed in 50% and 55% of the cases, respectively, in a cohort of 62 patients; interestingly, expression of PDGF-A and PDGFRα correlated with good prognosis." (PMID 24359404, 2013).